ZFPM2 (zinc finger protein, FOG family member 2)
Diseases named in the same sentence as ZFPM2 in open-access papers (continued):
Sharing a sentence is not in itself a finding about the gene and the disease.
psoriasis (1 paper, 2022). An autoimmune condition characterized by red, well-delineated plaques with silvery scales that are usually on the extensor surfaces and scalp. "Given that metabolic deterioration is the risk factor for both diseases, downregulating ZFPM2 should be the protective factor in psoriasis and AD, which contradicts our studies." (PMID 35669784, 2022). "Interestingly, ZFPM2 had high diagnostic values for psoriasis and AD either in the exploration cohort or validation cohort." (PMID 35669784, 2022). "Our work proposed that STFs (PPARG, ZFPM2, ZNF415, HLX, and ANHX) mediate the initiation of chronic inflammation and metabolic disorders that increase the risk of developing AD in the psoriasis population." (PMID 35669784, 2022). "Whether ZFPM2 affects the morbidity of psoriasis through epigenomic dysregulation needs further exploration." (PMID 35669784, 2022). "We identified 5 STFs (PPARG, ZFPM2, ZNF415, HLX, and ANHX) in common DEGs and investigated their potential roles in psoriasis and AD." (PMID 35669784, 2022). "Among these, four genes, PPARG, ZFPM2, ZNF415, and HLX, were down-regulated and ANHX upregulated in psoriasis and AD." (PMID 35669784, 2022). "The STFs (PPARG, ZFPM2, ZNF415, HLX, and ANHX) may increase the morbidity rate of AD in psoriasis by initiating a positive feedback loop of excessive inflammation and metabolic disorders." (PMID 35669784, 2022).
tricuspid atresia (1 paper, 2025). Tricuspid atresia is (TA) a rare congenital heart malformation characterized by the congenital agenesis of tricuspid valve leading to severe hypoplasia of right ventricle (functionally univentricular). "Patients in Group 1, the tricuspid atresia group, carried variants in the BMP2, MYH6, NFATC1, NOTCH1, and ZFPM2 genes, which have been reported to be associated with tricuspid atresia." (PMID 41153298, 2025).
tumor (17 papers, 2009 to 2025). "Accordingly, while a consolidated role has been established for GATA3 in human breast carcinogenesis, only few indirect observations suggest a protective role for ZFPM2/FOG2 in this tumor." (PMID 32290321, 2020). "Heterogeneity in the mutation frequencies was observed in the different tumor types with higher mutation rates found for PRDM3/MECOM, PRDM8, PRDM9, PRDM15, ZFPM1/FOG1 and ZFPM2/FOG2 in specific cancers." (PMID 30347759, 2018). "In a previous study conducted by our research group, ZFPM2 rs4734879 was found to be a prognostic factor among EOC patients, which was attributed to its potential influence in tumour neo-angiogenesis." (PMID 37308506, 2023). "Of note, TCGA gene expression profiling of PRDM genes revealed significant overexpression of PRDM12 and PRDM13 in many tumor types whereas ZFPM2/FOG2, PRDM8, and PRDM16 were more often downregulated in tumor tissues." (PMID 30347759, 2018). "A general differential expression, even though not significant, was observed for both ZFPM2/FOG2 and PRDM16 in several tumor tissues." (PMID 30347759, 2018).
cancer (9 papers, 2010 to 2025). A tumor composed of atypical neoplastic, often pleomorphic cells that invade other tissues. "Overall, PRDM2, PRDM3/MECOM, PRDM9, PRDM16 and ZFPM2/FOG2 were the most mutated genes with pan-cancer frequencies of protein-affecting mutations higher than 1%." (PMID 30347759, 2018). "Finally, ZFPM2/FOG2 was frequently mutated at a high rate in various cancer types, reaching a value of 11.1% in LUAD and 16.5% in SKCM." (PMID 30347759, 2018). "Similarly, the expression of the four MPM biomarker candidates LOX, LOXL1, LOXL2 and ZFPM2 were shown to be significantly increased in the MPM tissues when compared to the non-cancer patient samples." (PMID 31921422, 2020). "This upregulation of miR-141-3p and/or miR-200a-3p may have effects on several cancer-related target genes that have been previously associated with these two miRNAs, including E2F3, GLS, CCND2, PTEN, CCNG1, CDC25B, and ZFPM2." (PMID 28288173, 2017). "Specifically, PRDM12 and PRDM13 were largely overexpressed in many cancers whereas PRDM16 and ZFPM2/FOG2 were often downregulated." (PMID 30347759, 2018). "In the overall cohort, ZFPM2 rs4734879, SLC19 A2 rs2038024, ITGB3 rs5918 and GSR rs3779647 did not exhibit a significant impact on five-year DFS, regardless of genetic model (additive, recessive or dominant), sex (male vs. female) and cancer stage (III/IV vs. I/II or I/II/III vs. IV)." (PMID 40425987, 2025). "Finally, an interesting finding from a GWAS meta-analysis reported both ZFPM1 and ZFPM2 as genes influencing the circulating levels of the angiogenic vascular endothelial growth factor (VEGF), which is known to impact various physiological and disease processes including cancer." (PMID 32290321, 2020). "By comparing the lists of top-ranking cancer-related target genes, we were able to identify seven promising cancer-related genes that may be targets of the hsa_circRNA_100395/miR-141-3p/ miR-200a-3p axis in PTC (in order of descending rank): E2F3, GLS, CCND2, PTEN, CCNG1, CDC25B, and ZFPM2." (PMID 28288173, 2017).
cardiovascular disease (1 paper, 2024). "While circZFPM2 in cardiovascular disease remains functionally uncharacterized to date, the linear host gene, ZFPM2, encodes a zinc finger protein that primarily interacts with the GATA family of transcription factors to regulate hematopoiesis and cardiogenesis in mammals." (PMID 38639887, 2024).
ZFPM2 also shares sentences with these, for which no sentence is quoted: liver fibrosis (3 papers); ovarian tumors (3); heart failure (2); Insulin resistance (2); leukemia (2); psychiatric disorder (2); ventricular septal defect (2); acute myeloid leukemia (1); Alzheimer disease (1); atherosclerosis (1); atrial septal defect (1); breast carcinoma (1); campomelic dysplasia (1); capillary malformation (1); Cirrhosis (1); Cognitive impairment (1); colon cancer (1); congenital hypogonadotropic hypogonadism (1); Conotruncal Heart Defect (1); depression (1); developmental delay (1); diabetes (1); diaphragmatic defects (1); disorder of sex development (1); esophageal carcinoma (1); fatty liver (1); fibroma (1); Frasier syndrome (1); gastric cancer (1); gonadoblastoma (1).
A further 26 diseases each share a sentence with ZFPM2 in 1 paper.